ENSG00000277830
Gene: Miscellaneous RNA gene on chromosome 20 (49,278,427 to 49,278,624, forward strand). Ensembl gene ENSG00000277830.
Gene Ontology:
Cellular component: cytoplasm; nucleus